STC1 (stanniocalcin 1)
Diseases named in the same sentence as STC1 in open-access papers (continued):
Sharing a sentence is not in itself a finding about the gene and the disease.
cancer (continued). "It has been demonstrated that STC1 exhibited significant clinical value in the diagnosis, prognosis, and pathological parameters for many kinds of cancer patients." (PMID 35273656, 2022). "In this study, we compared the expression levels of STC1 in para-carcinoma tissues, OC tissues and peritoneal metastasis tissues." (PMID 35392966, 2022). "Single-cell sequencing assays and IHC analysis verified that STC1 expression was significantly enhanced in OC tissues compared with para-carcinoma tissues, and it was further up-regulated in peritoneal metastasis tissues compared with OC tissues." (PMID 35392966, 2022). "The results of single-cell sequencing and IHC assays verified that STC1 expression was significantly enhanced in OC tissues compared with para-carcinoma tissues, and it was further up-regulated in peritoneal metastasis tissues compared with OC tissues." (PMID 35392966, 2022). "In the future, uncovering molecules as well as signaling pathways that are involved in the growth of cancer cells downstream of STC‐1 will open possibilities for further clinical applications of STC‐1." (PMID 33826244, 2021). "Considerable numbers of clinical studies reported the dysregulation of STC1 in different types of cancers." (PMID 33156861, 2020). "Expression of STC1 is up‐regulated during the metastasis process induced by overexpression of PPARD in cancer cells, indicating a pro‐metastasis effect of STC1 on cancer." (PMID 32468698, 2020). "It has been reported that STC1 has a distinct clinical significance and is related to the diagnosis, pathological parameters and prognosis of cancer patients." (PMID 32468698, 2020). "What's more, it has been proved that STC1 is involved in multiple cancer‐related signalling pathways, such as NF‐kB,23 ERK1/224 and JNK signalling pathways." (PMID 32468698, 2020). "Experimental studies using different cancer cell models unraveled the roles of STC1 in cell proliferation/apoptosis, inflammation, migration, and angiogenesis." (PMID 33156861, 2020). "Collectively, this is the first report to demonstrate the inhibitory effect of STC1-overexpressing cancer cells on macrophage migration/infiltration." (PMID 33156861, 2020). "STC1, involved in various cancer-related signaling pathways, induces VEGF expression in GC cells and NRP1 induces proliferation, migration, and metastasis of GC cells." (PMID 33302481, 2020). "Given that the expressions of p16INK4A and p21CIP1/WAF1, cyclin-dependent kinase inhibitors, are strongly affected by the ageing of cancer cells or MSCs, we next determined the expression of these genes in TMSCs after STC1 inhibition." (PMID 32155780, 2020). "Many studies have shown that overexpression of STC1 with high levels of mRNA and protein in serum and cancer tissues compared with normal counterparts correlates with a poor prognosis of patients." (PMID 32468698, 2020). "In the Boyden chamber experiments with or without the monocyte chemoattractant protein-1 (MCP-1/CCL2), THP-1 cells co-cultured with STC1-overexpressing cancer cells showed a significant reduction in migration." (PMID 33156861, 2020). "Recent studies also verified that STC1 promotes carcinogenesis in most kinds of cancer, for it prevents cellular apoptosis, promotes cancer cell viability, proliferation and invasiveness." (PMID 32468698, 2020). "MSCs can secrete STC1 to protect cancer cells from apoptosis by reducing reactive oxygen radical (ROS), it suggests that STC1 play an important role in antioxidant activity of MSCs." (PMID 32489333, 2020). "Immunohistochemistry staining (IHC) and immunofluorescence were also used to examine the expression and localization of STC1 in ccRCC tissues and cancer cells." (PMID 25740019, 2015). "The elevated expression levels of STC1 identified in patients with different cancer types was found to correlate to poor prognosis; hence, the use of STC1 as a molecular marker for cancer progression has been suggested." (PMID 26469082, 2015).
cancer (continued). "Experiments revealed that the migration and invasion of cancer cells were significantly decreased following knockdown of STC1 when compared with controls (P < 0.05)." (PMID 25740019, 2015). "In clinicopathological study of STC1 functions, significant elevated STC1 expression levels were mostly detected in different human cancer samples, such as tumors of lung, breast, ovary, colon, pancreas, and liver." (PMID 26469082, 2015). "Growing evidence has revealed high expression levels of stanniocalcin-1 (STC1) in different types of human cancers." (PMID 26469082, 2015). "Recently, a series of studies revealed the involvement of STC1 in cancer progression and metastasis, which motivated us to focus on the role of STC1 in ccRCC development and progression." (PMID 25740019, 2015). "Numerous experimental studies using cancer cell lines demonstrated the involvement of STC1 in inflammatory and apoptotic processes; however the role of STC1 in carcinogenesis remains elusive." (PMID 26469082, 2015). "H&E staining of STC1 overexpressed tumors showed a low nuclear/cytoplasmic ratio, and limited to the cancer nests compared to control tumors." (PMID 23382863, 2013). "Despite of enhanced knowledge of STC1, there is little known function of STC1 in cancer progression." (PMID 23382863, 2013). "An earlier study demonstrated the HIF-1 protein mediated activation of STC1 expression in hypoxic human cancer cells." (PMID 23145134, 2012). "We previously reported that STC1 was expressed in various human cancer cell lines as well as in human colorectal, breast, stomach, esophageal, biliary tract, and liver tumors." (PMID 22200953, 2012). "STC1, involved in calcium homeostasis, has been reported to have osteoblastic and angiogenic modulator properties with altered expression in some cancers." (PMID 17430594, 2007). "Previously, STC1 exerts an important effect on other cancer types." (PMID 40741411, 2025). "In summary, STC1 is a potential regulator of cancer cell and stroma interactions." (PMID 39807836, 2025). "Differential STC1 mRNA expression between GC and non-carcinoma tissues was examined." (PMID 40741411, 2025). "Thirdly, while we identified potential mechanisms through which STC1 may influence cancer progression, more detailed molecular studies are required to unravel the precise pathways involved." (PMID 39668832, 2024). "However, based on the regulation of calcium and phosphorus by STC1, safety problems targeting STC1 should be considered, and further researches are required to insure above approaches can bring clinical benefits for cancer." (PMID 39654892, 2024). "However, the specific mechanisms through which STC-1 interacts with other components of the immune system and its broader implications for cancer therapy are still under investigation." (PMID 38881902, 2024). "STC1 has been associated with disease progression, survival, metastasis, and negative prognosis in cancer patients." (PMID 39012409, 2024). "Specifically, STC1 decreased the “eat me” signal by down-regulating the expression of CRT on the membrane of cancer cells, affecting the recognition of cancer cells by antigen presenting cells such as TAMs and DCs, and further interfered with the specific recognition of T cells." (PMID 39654892, 2024). "Neutrophils were positively related to STC1 in most cancers, especially COAD and STAD." (PMID 39201771, 2024). "Since both EMT and CSCs are intimately involved in drug resistance in cancer, we speculated that STC1 also participates in the drug resistance." (PMID 38380370, 2024). "In cancer, STC1 enhances metastasis via the PI‐3K/Akt/NF‐kB signaling pathways." (PMID 38217262, 2024). "Additionally, by conducting a pan-cancer analysis of STC1, the expression patterns and functional roles of STC1 in various cancer types were discerned, shedding light on potential biomarkers or therapeutic targets." (PMID 39201771, 2024). "In the context of cancer, STC-1 can be viewed as a potential therapeutic target." (PMID 38881902, 2024).
cancer (continued). "Stanniocalcin-1 (STC-1) is a glycoprotein hormone that affects the progression of cancers." (PMID 39071498, 2024). "It has been revealed that extracellular ATP could induce STAT3 signaling and NF-κB pathway activation, which links inflammation to cancer and is related to the release of some chemokines and STC1." (PMID 37158903, 2023). "In addition, abnormally high expression of STC1 has also been found in a variety of cancers and has been shown to promote the initiation and development of tumors." (PMID 37004088, 2023). "Stanniocalcin‐1 (STC1) promoted different types of cancer progression." (PMID 37543714, 2023). "In addition, enhanced expression of STC1 has been identified in various cancers, such as breast cancer, hepatocellular carcinoma and glioblastoma." (PMID 35392966, 2022). "STC1 is commonly upregulated in various cancer types and correlates with poor prognosis." (PMID 35152264, 2022). "As some preclinical studies and clinical data have demonstrated the promise of targeting phagocytosis checkpoints, macrophage phagocytosis checkpoints, including CD47, CD24, stanniocalcin 1 (STC1), are potential targets for cancer immunotherapy in patients with advanced cancers." (PMID 35152264, 2022). "Furthermore, we found that the expression of STC1 was up-regulated in OC tissues compared with para-carcinoma tissues and was further increased in peritoneal metastasis tissues (red region)." (PMID 35392966, 2022). "However, the molecular function of STC1 is still elusive due to heterogeneity among different cancer types, leading to contradictory results and dampening the application potential of STC1 in clinical settings." (PMID 34722511, 2021). "Overall, our data may suggest a favorable role for STC-1 in EC behavior; however, further studies are required to elucidate the detailed mechanism and possible applications to cancer treatment." (PMID 34650342, 2021). "Moreover, macrophage-capping protein (CAPG) has been shown to promote cancer metastasis, STC-1 enhances the invasion of cancer cells by activating PI3K pathway." (PMID 34513846, 2021). "It was demonstrated that STC1 plays a role in cell differentiation and cell growth, and the expression of STC1 could be aberrant in cancer, although the function of STC1 remains unclear." (PMID 33946970, 2021). "Stanniocalcin-1 (STC-1) is a glycoprotein hormone involved in diverse biological processes, including regulation of calcium phosphate homeostasis, cell proliferation, apoptosis, inflammation, oxidative stress responses, and cancer development." (PMID 34650342, 2021). "Activation of PDGFRb, in particular on fibroblasts, has also been demonstrated to induce an upregulation of hepatocyte growth factor (HGF) and stanniocalcin-1 (STC1), with the latter having furthermore been linked to increased distant metastasis in several murine cancer models." (PMID 33661437, 2021). "It is well-recognized that STC1 expression is deregulated in human cancers." (PMID 32579928, 2020). "There is growing evidence on the aberrant expression of STC1 in various types of cancers." (PMID 33156861, 2020). "Therefore, we will discuss the possible mechanisms through which STC1 interacts with cancer cells and its clinical relevance in this review." (PMID 32468698, 2020). "The STC1 expression level has a close connection with the prognosis of cancer patients." (PMID 32468698, 2020). "Klein et al64 demonstrated that STC1 is a target gene of Wnt signalling and can be down‐regulated by Wnt2, which acts as an angiogenic growth factor and differentiation factor in vascular development during cancer progression." (PMID 32468698, 2020).
cancer (continued). "So we want to explore the function of STC1 thoroughly for it may be regulated by many cancer‐related factors." (PMID 32468698, 2020). "Therefore, STC1 promotes cancer cell proliferation via a novel mechanism through which several cyclins and CDKs are recruited to regulate the cell cycle positively." (PMID 32468698, 2020). "Research regarding the functions of LOXL2 and STC1 in cancer development is limited." (PMID 32139696, 2020). "In such cases, MSCs reduce intracellular ROS in cancer cells in organs such as the lung through the secretion of substances that uncouple oxidative phosphorylation and direct metabolism towards glycolysis, like stanniocalcin-1 (STC1)." (PMID 28473858, 2017). "Although most of studies have focused on the calcium-regulating functions of STC1, increasing evidence suggests that STC1 may also play a major role in carcinoma." (PMID 28545028, 2017). "The hypothesis that E-MpM is made up of cells with stem-like properties was also supported by the results obtained by applying the cancer stem cell profiler complemented by PCR to STC1." (PMID 27705913, 2016). "Like cancer cells, placental cells are characterized by invasive nature and migratory properties which may partly support the function of STC1 in ccRCC cells." (PMID 25740019, 2015). "Some of them have also been shown to be involved in cancer progression such as STC1 and ZNF395." (PMID 25122487, 2014). "Instead, the anti- or pro-apoptotic roles of STC1 may vary depending on the source, stage, or subset of cancer cells." (PMID 24743310, 2014). "Aberrant expression of STC1 or STC2 correlates with poor prognosis in multiple types of cancer." (PMID 24743310, 2014). "STC1 was originally cloned in a screen for cancer-related genes." (PMID 23382863, 2013). "A human ortholog of fish STC1 was found by mRNA differential display of cancer related genes." (PMID 23382863, 2013). "Furthermore, in the 40 PB and/or BM samples from patients with benign esophageal disease, only 2 cases (5.0%) were found to be STC-1 mRNA-positive, this frequency was remarkably lower than that in the cancer patients (P < 0.001)." (PMID 22537917, 2012). "However, the exact role for STC-1 in inducing both tumorigeneisis and angiogenesis in cancer is not well understood." (PMID 21672207, 2011). "However, the specific mechanisms of STC-1 in cancer still require further investigation." (PMID 39071498, 2024). "Moreover, STC1 expression is significantly associated with MMR, TMB, and MSI, as well as DNA methylation, all of which indicate that STC1 may affect cancer prognosis and immunology." (PMID 39201771, 2024). "In cancer, STC1 may promote metastasis through new angiogenesis." (PMID 37988196, 2023). "Furthermore, our results of untargeted relative quantitative lipidomic assays indicated that compared with control cells, STC1 knockdown cancer cells contained decreased amounts of TGs (such as 16:0 and 18:0) and increased amounts of PCs (such as 36:0) and Cers (such as d18:1)." (PMID 35392966, 2022). "Therefore, STC1 holds promise as a biomarker in the early diagnosis of cancer." (PMID 35273656, 2022). "Moreover, the researches about STC1 and cancer are more abundant than STC2." (PMID 32468698, 2020). "Furthermore, the serum level of STC1 mRNA serves as a molecular marker for micrometastases of various human cancers because STC1 mRNA might be useful to detect cancer cells in blood." (PMID 32468698, 2020). "Exploring the role of STC1 in cancer development may provide a better understanding of the tumorigenesis process in humans and may facilitate finding an effective therapeutic method against cancer." (PMID 32468698, 2020). "On the other hand, overexpression of STC1 caused dwarfism and bone defects, which may imply that aberrant concentrations, as reported for cancer, might induce additional effects not seen in the knockout models." (PMID 32364536, 2020).
cancer (continued). "Furthermore, expression of STC1 is elevated, which functions as a mediator during the metastasis process induced by platelet‐derived growth factor (PDGF), a major functional determinant of cancer‐associated fibroblasts (CAFs)." (PMID 32468698, 2020). "Specifically, genes such as STC1 (PAI 6: Vertebrata), VCAN (PAI 7: Euteleostomi), and SPP1 (PAI 9: Eutheria)—key regulators of such hallmarks of cancer as angiogenesis and metastasis in tumors." (PMID 40507851, 2025). "We investigated the physiologic STC1 protein expression levels in different cell lines using the HPA database and discovered that it was detected in many cell lines and had low cancer specificity." (PMID 39201771, 2024). "On the other hand, the connection between STC1 expression and MSI reached statistical significance (p < 0.05) in eight different cancer types." (PMID 39201771, 2024). "Overall, our findings, combined with those from other studies, highlight the potential of STC-1 as a promising therapeutic target in OSCC and other cancers." (PMID 39071498, 2024). "Recent studies have confirmed that STC1 is overexpressed and regulates CSC-like properties in various cancers." (PMID 39103836, 2024). "In twenty different forms of cancer, including PAAD, THCA, and UVM, STC1 expression is shown to be significantly related to these four DNA methyltransferases." (PMID 39201771, 2024). "According to the findings, there is a substantial correlation between the expression of STC1 and the expression of MMR genes in 21 different forms of cancer (p < 0.05), significantly in THCA, PAAD, KIRP, and READ." (PMID 39201771, 2024). "Immunohistochemical staining showed that the expression of STC1, AKR1B1, and CD47 was increased along cancer invasion." (PMID 36816947, 2023). "Phagocytosis checkpoints, such as CD47, CD24, MHC-I, PD-L1, STC-1 and GD2, have emerged as essential checkpoints for cancer immunotherapy by functioning as “don’t eat me” signals or interacting with “eat me” signals to suppress immune responses." (PMID 36882399, 2023). "Immunohistochemic3al staining showed the expression of STC1, AKR1B1, and CD47 was increased along cancer invasion in CRC samples." (PMID 36816947, 2023). "One study found that POLE2 regulates its downstream oncogene STC1, activates AKT phosphorylation, decreases HIF-1α expression levels, and promotes cancer cell proliferation." (PMID 37240068, 2023). "The expression of STC1, AKR1B1, RPL5, and CD47 was increased, while HLA-A was downregulated along cancer invasion by immunohistochemical staining in clinical samples." (PMID 36816947, 2023). "Considering the functional roles of STC1, including EMT-inducing functions, which have been reported in other cancer types, it is conceivable that STC1 has a general function in inducing EMT and CSC formation in other cancer types as well." (PMID 36499099, 2022). "It is possible that STC1 and PENK could act in concert towards differentiation, with additional contribution from many other differentially expressed candidate genes between CD49a+ prostate and CD13+ bladder stromal cells, between CD49a+ prostate stromal and CD90+ cancer-associated stromal cells." (PMID 34911496, 2021). "In addition, an increased STC1 expression level after protein phosphatase magnesium‐dependent 1 delta (PPM1D) silencing indicated that STC1 was affected by PPM1D, a protein overexpressed in various cancer cell lines, which has been associated with poor prognoses of cancers." (PMID 32468698, 2020). "Furthermore, a specific antagonist of STC1 may be a potential therapeutic drug for cancer." (PMID 32468698, 2020). "In a clinicopathological study of stanniocalcin-1 functions, significant elevated STC1 expression levels were described in different human cancer samples, such as tumors of lung, breast, ovary, or liver." (PMID 31581653, 2019).